MTUS1 (microtubule associated scaffold protein 1)
Description:
Cooperates with AGTR2 to inhibit ERK2 activation and cell proliferation. May be required for AGTR2 cell surface expression. Together with PTPN6, induces UBE2V2 expression upon angiotensin-II stimulation. Isoform 1 inhibits breast cancer cell proliferation, delays the progression of mitosis by prolonging metaphase and reduces tumor growth.
Synonyms: ATBP; ATIP; KIAA1288; MTSG1; DKFZp586D1519; FLJ14295; ATIP1; MP44; ICIS; ATIP3
Tractability: Antibody: UniProt places it where antibodies can reach, with medium confidence; its Gene Ontology location is reachable by antibodies, with medium confidence. PROTAC: ubiquitination databases record sites on it; its protein half-life has been measured.
Gene: Protein-coding gene on chromosome 8 (17,643,794 to 17,801,545, reverse strand). Ensembl gene ENSG00000129422.
Subcellular location: Mitochondrion; Golgi apparatus; Cell membrane; Nucleus; Cytoplasm, cytoskeleton, microtubule organizing center, centrosome (Isoform 1); Cytoplasm, cytoskeleton, spindle
Subcellular location (Human Protein Atlas): Microtubules; Nucleoli
Gene Ontology:
Molecular function: microtubule binding
Biological process: regulation of macrophage chemotaxis
Cellular component: extracellular region; microtubule cytoskeleton; nucleolus; cytoplasm; nucleus; centrosome; Golgi apparatus; mitochondrion; plasma membrane; spindle
Genetic constraint (gnomAD): Loss-of-function variants: 86 observed, 100.69 expected, observed/expected ratio (o/e) 0.85, 90% interval 0.72 to 1.02. The synonymous counts are far from expectation, so gnomAD's model fits this gene poorly and the ratio says little. Missense variants: 2,017 observed, 1,424.1 expected, observed/expected ratio (o/e) 1.42, 90% interval 1.37 to 1.47. Synonymous variants: 682 observed, 533.73 expected, observed/expected ratio (o/e) 1.28, 90% interval 1.2 to 1.36.
Homologues: Orthologues: chimpanzee MTUS1 (98% identical), macaque MTUS1 (93% identical), rabbit MTUS1 (77% identical), dog MTUS1 (75% identical), guinea pig MTUS1 (73% identical), pig MTUS1 (71% identical), mouse Mtus1 (63% identical), rat Mtus1 (63% identical), tropical clawed frog mtus1 (36% identical), zebrafish mtus1b (17% identical), zebrafish mtus1a (16% identical). Paralogues in human: MTUS2 (20% identical), CCDC69 (7% identical).
Diseases named in the same sentence as MTUS1 in open-access papers:
MTUS1 is named in the same sentence as 80 diseases in open-access papers, as found by Europe PMC text mining. Sharing a sentence is not in itself a finding about the gene and the disease. The quoted sentences say what the papers report.
breast carcinoma (23 papers, 2004 to 2024). "At the genomic level, alterations of ATIP3-specific coding exons by somatic mutation have been identified in hepatocellular carcinoma but mutational analysis of MTUS1 in breast cancer remains to be performed." (PMID 34062782, 2021). "A deletion polymorphism spanning a MTUS1 coding exon has been shown to significantly associate with decreased risk of familial breast cancer." (PMID 19794912, 2009). "Recent studies have reported that recombinant overexpression of MTUS1 inhibited tumor cell proliferation, while reduced MTUS1 expression was associated with increased cell proliferation of oral squamous cell carcinoma cells, breast cancer cells, and ovarian cancer cells." (PMID 36980447, 2023). "MTUS1 Affymetrix probeset intensities were significantly lower in a majority (83.3%) of triple negative (ER−/PR−/HER2−) carcinomas as compared to luminal (ER+) and HER2+ tumor subgroups, which supports the conclusion that reduced levels of MTUS1 are associated with breast cancer aggressive subtypes." (PMID 19794912, 2009). "Rodrigues-Ferreira investigated the predictive value in breast cancer of 280 genes encoding proteins involved in microtubule functions; finding the MTUS1 gene and its codified protein ATIP3 as predictive biomarkers to taxanes." (PMID 38329732, 2024). "MTUS1 expression is downregulated in several types of malignancies, such as breast cancer 37, colorectal carcinoma 38 and gastric cancer." (PMID 38725862, 2024). "Several pathogenic CNVs in special genes have been reported in the beginning and development of breast cancer subtypes, including BRCA1, MTUS1, and hTERT, suggesting that CNVs also play a unique role in breast cancer." (PMID 36685905, 2022). "With the aim of identifying new molecular markers in breast cancer, the expression levels of the MTUS1 gene were analyzed in a DNA array study of 151 breast tumors compared to normal breast tissue." (PMID 34062782, 2021). "Several pathological CNVs, such as CNV of BRCA1, MTUS1 and hTERT, have been identified in the initiation and progression of breast cancer subtypes, suggesting a specific contribution of CNVs to breast cancer." (PMID 34364397, 2021). "This review focuses on ATIP3, a potent anti-cancer protein encoded by candidate tumor suppressor gene MTUS1, whose expression levels are markedly down-regulated in breast cancer." (PMID 34062782, 2021). "Data in the literature show that the expression of Mtus1 is down-regulated in a wide range of cancers: colon tumors, breast cancer, ovarian cancer, head and neck squamous cell carcinoma, as well as prostate cancer cell lines." (PMID 30284595, 2019). "TRERF1 and MTUS1 are reported to be involved in the differentiation in breast cancer cells and oral tongue squamous cell carcinoma, respectively." (PMID 30171794, 2018). "Previous studies have shown that MTUS1 expression levels are down-regulated in cancers of the colon, ovary, pancreas, head and neck, and breast cancer." (PMID 25079112, 2014). "MTUS1 expression levels were significantly reduced in breast cancer samples as compared to normal tissue." (PMID 19794912, 2009). "The present study investigates the expression levels and biological effects of MTUS1 gene products in infiltrating breast cancer." (PMID 19794912, 2009). "The present study investigates the expression and functional effects of MTUS1 gene products in breast cancer." (PMID 19794912, 2009). "The mitochondrial tumor suppressor (MTUS1) gene localizes at 8p22, a chromosomal region frequently deleted in epithelial cancers including in poor prognosis breast cancer." (PMID 19794912, 2009). "MTUS1 immunostaining was then analyzed in 20 breast cancer samples for which paraffin-embedded tissue sections were available." (PMID 19794912, 2009). "MTUS1 can also regulate cell division by disturbing the microtubule cytoskeleton and can also be used to predict the treatment response to paclitaxel-based chemotherapy in breast cancer." (PMID 35962436, 2022).
breast carcinoma (continued). "For example, SORBS2 inhibited renal clear cell carcinoma metastasis by enhancing MTUS1 mRNA stability; RBM38 increased PREN stability and enhanced its expression to promote breast cancer progression progress." (PMID 36463205, 2022). "Meanwhile, in brain and CNS cancers, breast cancer, CRC, head and neck cancer, kidney cancer, ovarian cancer, sarcoma, and lung cancer, MTUS1 mRNA expression was lower than that in adjacent normal controls." (PMID 35962436, 2022). "Many studies had found that the deregulation of MTUS1/ATIP is related to many types of cancer, such as hepatocellular carcinoma, bladder cancer, breast cancer, colon cancer, prostate cancer and head and neck cancer." (PMID 25885343, 2015). "Although this possibility has not been directly addressed in breast cancer, recent studies have indeed reported promoter methylation as a possible mechanism for MTUS1 down-regulation in non-small cell lung (NSCLC) carcinoma." (PMID 34062782, 2021). "Significant correlation was observed between Affymetrix probeset intensities and expression levels of ATIP3 (r2 = 0.83), but not ATIP1 transcripts (r2 = 0.01), indicating that ATIP3 is the major MTUS1 splice variant whose expression is regulated in breast cancer." (PMID 19794912, 2009). "Nine out of 13 breast cancer cell lines including MDA-MB-231, MCF7, Hs578T, BT549, MDA-MB-453, T-47D, ZR-75.1, MDA-MB-361 and SK-BR3 showed low to undetectable levels of MTUS1, whereas CAMA-1, ZR-75.30, BT-474 and MDA-MB-468 expressed moderate levels of MTUS1 transcripts." (PMID 19794912, 2009).
lung carcinoma (11 papers, 2009 to 2025). "Westcott and his colleagues recorded the mutational landscapes of KRAS driven lung cancer, knockdown of MTUS1 expedited growth in a mouse lung cancer cell line caused by KRAS G12D79." (PMID 41203700, 2025). "In lung cancer, the microtubule-associated tumor suppressor 1 (MTUS1) gene is influenced by miR-19a and miR-19b, which are part of a miRNA cluster containing oncogenes." (PMID 39908270, 2025). "Downregulation or loss of MTUS1 is a frequent event and indicator of poor survival in bladder carcinomas, lung cancer, salivary adenoid cystic carcinoma, gastric cancer, and breast cancer." (PMID 33311452, 2020). "The target of this study was to evaluate the association between MTUS1 gene expression and lung cancer and to identify the molecular pathways associated with MTUS1 regulation." (PMID 28364280, 2017). "In summary, this study not only elucidated the critical role of MTUS1 as a tumor suppressor in lung cancer but also explored the molecular mechanisms underlying MTUS1 regulation and identified miR-19a/b as direct upstream regulators of MTSU1 expression." (PMID 28364280, 2017). "First, MTUS1 was proved to function as a tumor suppressor in lung cancer and was linked to cell proliferation and migration promotion." (PMID 28364280, 2017). "The mechanism underlying MTUS1 downregulation in lung cancer tissues remains largely unknown." (PMID 28364280, 2017). "Several studies have further investigated the function of MTUS1 using various lung cancer cell lines." (PMID 34359333, 2021). "Previous cell proliferation and migration studies with the A549 lung cancer cell line have confirmed the potential role of MTUS1 as a tumor suppressor." (PMID 34359333, 2021). "Correspondingly, MTUS1 mRNA levels were consistently downregulated in lung cancer tissues compared with normal tissues." (PMID 28364280, 2017). "In the present study, we reported that miR-19a and miR-19b (miR-19a/b) promote proliferation and migration of lung cancer cells by targeting MTUS1." (PMID 28364280, 2017). "After measuring the levels of MTUS1 protein expression in 9 pairs of lung cancer tissue samples and corresponding normal adjacent tissue samples, we found that MTUS1 protein levels were significantly lower in lung cancer tissues than in normal tissues." (PMID 28364280, 2017). "Second, an inverse correlation between miR-19a/b expression and MTUS1 mRNA/protein expression was noted in human lung cancer tissues." (PMID 28364280, 2017). "Fourth, direct MTUS1 regulation by miR-19a/b in lung cancer cells was experimentally affirmed by cell transfection assay and luciferase reporter assay." (PMID 28364280, 2017). "Although several papers regarding the relationship between MTUS1 gene expression and cancer have been published, very little is known regarding the role and regulation of MTUS1 in lung cancer." (PMID 28364280, 2017). "In conclusion, our findings have provided the first clues regarding the roles of miR-19a/b, which appear to function as oncomirs in lung cancer by downregulating MTUS1." (PMID 28364280, 2017). "These indicate that MTUS1 negatively modulates lung cancer cell proliferation and migration to exert its tumor suppressor effects." (PMID 28364280, 2017). "Next, we identified miR-19a/b as a potential regulator of MTUS1 using bioinformatics analysis and experimentally confirmed that MTUS1 is directly regulated by miR-19a/b in lung cancer cells." (PMID 28364280, 2017). "The correlation between miR-19a/b and MTUS1 was examined further by evaluating MTUS1 expression in three lung cancer cell lines (A549, H1975, and HCC827) in the setting of miR-19a/b overexpression or knockdown." (PMID 28364280, 2017). "Highest levels of MTUS1 expression were found in the lung cancer cell line SK-MES, that was therefore selected for further study." (PMID 19794912, 2009). "These miRNAs inhibit MTUS1, which then leads to lung cancer." (PMID 39908270, 2025).
lung carcinoma (continued). "Moreover, MTUS1 expression levels can be synergistically inhibited by miR-19a and miR-19b, thereby contributing to lung cancer cell proliferation and migration." (PMID 35962436, 2022). "MTUS1 is a tumor suppressor in lung cancer that promotes cell proliferation and migration." (PMID 34476221, 2021). "We next evaluated the biological functions of MTUS1 in lung cancer cell line A549." (PMID 28364280, 2017). "Taken together, these results indicate that miR-19a/b may regulate the proliferation, migration, and invasion of lung cancer cells through a MTUS1-dependent manner." (PMID 28364280, 2017). "Although several papers regarding the relationship between MTUS1 gene expression and cancer have been published, the roles of MTUS1 in the development of human cancers (especially lung cancer) remain unclear." (PMID 28364280, 2017). "Therefore, miRNAs likely play a biologically relevant role in regulating MTUS1 expression in lung cancer." (PMID 28364280, 2017). "Thus, this study delineated a novel regulatory network employing miR-19a/b and MTUS1 to regulate lung cancer cell fates." (PMID 28364280, 2017). "Finally, miR-19a/b were shown to cooperatively repress MTUS1 expression and synergistically regulate MTUS1 expression to promote lung cancer cell proliferation and migration." (PMID 28364280, 2017). "Because miRNAs generally exhibit expression patterns that contrast with those of their targets, we investigated whether miR-19a/b expression levels were inversely correlated with MTUS1 expression levels in lung cancer." (PMID 28364280, 2017). "In this study, we found that MTUS1 functions as a tumor suppressor in lung cancer cells." (PMID 28364280, 2017). "As a single miRNA can target hundreds of genes, it is necessary to determine whether the effects of miR-19a/b on lung cancer cells are derived from miR-19a/b-mediated MTUS1 suppression." (PMID 28364280, 2017). "Finally, we showed that MTUS1 is synergistically suppressed by miR19a/b, resulting in lung cancer cell proliferation and migration." (PMID 28364280, 2017). "In particular, hsa-mir-19a affects the survival at the first stage, which regulates biological molecules such as grape seed procyanidin, MTUS1, c-Met, and FOXP1 to affect lung cancer." (PMID 32428028, 2020).
colorectal cancer (9 papers, 2012 to 2025). A primary or metastatic malignant neoplasm that affects the colon or rectum. "Abnormally expressed MTUS1 is closely linked with colorectal cancer and prostate cancer." (PMID 38033505, 2023). "In colorectal carcinoma (CRC), miR-184 was upregulated while microtubule-associated tumour suppressor 1 (MTUS1) was reduced compared to controls." (PMID 41379397, 2025). "The role of microRNAs in controlling MTUS1 expression has also been studied in breast and colorectal cancers." (PMID 34359333, 2021).
prostate carcinoma (8 papers, 2011 to 2023). A carcinoma that arises from epithelial cells of the prostate gland. "Mitochondrial tumor suppressor 1 (MTUS1) is a tumor suppressor gene which has been associated with various cancers i.e. breast, colon, lung, pancreas, bladder and prostate cancer." (PMID 34125870, 2021). "Our most promising candidate gene identified in aCGH at 8p22, MTUS1, is known to be downregulated in other cancer entities, such as pancreatic, ovarian, colon, breast and prostate cancer." (PMID 24650297, 2014). "The AT2-receptor, through an interaction with its putative signaling partner MTUS1/ATIP (AT2-receptor interacting protein), inhibits the mitogenic effects of EGF in prostate cancer cell lines representing both early and late stage disease." (PMID 24213113, 2011).
cardiac hypertrophy (7 papers, 2012 to 2025). "According to the mouse phenome browser, the gene MTUS1 is linked to both cardiac hypertrophy and B-cell lymphoproliferative disease in the mouse." (PMID 37277858, 2023). "By performing genome-wide exon array analysis in hypertrophic murine hearts induced by TAC surgery, Ito and colleagues successfully identified Mtus1A, one of the splice variants of mitochondrial tumor suppressor 1 (Mtus1), as a central modulator in hemodynamic stress-induced cardiac hypertrophy." (PMID 35118147, 2021). "On the other hand, adult MTUS1 knockout mice have elevated blood pressure and develop spontaneous heart hypertrophy compared to wild-type mice." (PMID 40004439, 2025). "Both issues must be addressed for further understanding the development of heart hypertrophy in MTUS1 KO mice." (PMID 22200760, 2012). "In conclusion, we report here the generation of the first MTUS1 KO mouse line, which develops spontaneous heart hypertrophy and SLE-like lymphoproliferative disease." (PMID 22200760, 2012). "Twenty-eight percent of the studied MTUS1 KO mice developed heart hypertrophy and 12% developed glomerulonephritis." (PMID 22200760, 2012). "A recently published study showed that MTUS1 knock-out mice developed spontaneous heart hypertrophy, suggesting that MTUS1 may affect cardiovascular system development." (PMID 31338350, 2019). "On the other hand, the overexpression of certain MTUS1 gene transcripts reduced cardiac hypertrophic remodeling in mouse models subjected to pressure overload or phenylephrine treatment, preventing both a beneficial adaptive phase and a maladaptive phase of cardiac hypertrophy." (PMID 40004439, 2025). "MTUS1 could therefore prevent heart hypertrophy in two ways." (PMID 22200760, 2012). "Twenty-eight percent of the studied MTUS1 KO mice also developed heart hypertrophy and 12% developed nephritis, independent of blood pressure levels." (PMID 22200760, 2012).
hepatocellular carcinoma (7 papers, 2009 to 2023). A malignant tumor that arises from hepatocytes. "Of interest, our previous mutational analysis of MTUS1 in a series of hepatocellular carcinomas and cell lines has identified five potential gene mutations which are all located in exons specific to the ATIP3 transcript." (PMID 19794912, 2009). "Various nucleotide substitutions have been reported in the coding region of the MTUS1 gene in hepatocellular carcinoma, and head and neck squamous cell carcinoma." (PMID 36980447, 2023).
gastric cancer (6 papers, 2015 to 2024). A primary or metastatic malignant neoplasm involving the stomach. "Additionally, recent studies have shown that MTUS1 loss or downregulation is associated with enhanced tumor proliferation, poor tumor differentiation, and poor prognosis in bladder cancer, gastric cancer, salivary adenoid cystic carcinoma, and other cancers." (PMID 28364280, 2017). "Secondly, the ‘Target’ run with MTUS1 as the target gene represented that altered genes of Gastric cancer (i." (PMID 34125870, 2021). "MTUS1 has a significant impact on the proliferation and metastatic potential of gastric cancer cell lines, as it has shown a potential anticancer effect in gastric cancer cell lines." (PMID 34476221, 2021). "For instance, in case of gastric cancer, the expression of CCNB2, OIP5 etc. genes were found to be altered along with MTUS1 mutation." (PMID 34125870, 2021).
ovarian carcinoma (6 papers, 2012 to 2025). A malignant neoplasm originating from the surface ovarian epithelium. "MTUS1 was first identified as a novel tumor suppressor in pancreatic malignancy and in various types of cancers including breast, head and neck, colon, and ovarian cancers, and its downregulation has been confirmed." (PMID 36980447, 2023). "Among top 20 ranked miRNA-mRNA interaction pairs, the roles of four targets including PLAGL1, MTUS1, MEF and IFNGR1 have been reported in ovarian cancer." (PMID 25079112, 2014).